SPAG5 (sperm associated antigen 5)
Description:
Essential component of the mitotic spindle required for normal chromosome segregation and progression into anaphase. Required for chromosome alignment, normal timing of sister chromatid segregation, and maintenance of spindle pole architecture. In complex with SKAP, promotes stable microtubule-kinetochore attachments. May contribute to the regulation of separase activity. May regulate AURKA localization to mitotic spindle, but not to centrosomes and CCNB1 localization to both mitotic spindle and centrosomes. Involved in centriole duplication. Required for CDK5RAP2, CEP152, WDR62 and CEP63 centrosomal localization and promotes the centrosomal localization of CDK2. In non-mitotic cells, upon stress induction, inhibits mammalian target of rapamycin complex 1 (mTORC1) association and recruits the mTORC1 component RPTOR to stress granules (SGs), thereby preventing mTORC1 hyperactivation-induced apoptosis. May enhance GSK3B-mediated phosphorylation of other substrates, such as MAPT/TAU.
Synonyms: MAP126; DEEPEST; hMAP126
Tractability: PROTAC: ubiquitination databases record sites on it.
Gene: Protein-coding gene on chromosome 17 (28,577,565 to 28,599,025, reverse strand). Ensembl gene ENSG00000076382.
Subcellular location: Cytoplasm; Cytoplasm, cytoskeleton; Cytoplasm, cytoskeleton, spindle; Cytoplasm, cytoskeleton, spindle pole; Chromosome, centromere, kinetochore; Midbody; Cytoplasm, cytoskeleton, microtubule organizing center, centrosome; Cytoplasmic granule; Cytoplasm, cytoskeleton, microtubule organizing center, centrosome, centriolar satellite
Subcellular location (Human Protein Atlas): Mitotic spindle; Nuclear bodies; Cytosol
Gene Ontology:
Molecular function: microtubule binding; protein binding
Biological process: chromosome segregation; mitotic sister chromatid segregation; positive regulation of intracellular transport; positive regulation of spindle assembly; protein localization to centrosome; regulation of attachment of spindle microtubules to kinetochore; regulation of metaphase plate congression; spindle organization; cell division
Cellular component: centriolar satellite; cytoplasm; cytosol; kinetochore; microtubule plus-end; mitotic spindle; mitotic spindle pole; nuclear body; centrosome; ciliary basal body; ciliary rootlet; cytoskeleton; midbody; spindle; spindle pole
Genetic constraint (gnomAD): Loss-of-function variants: 99 observed, 153.07 expected, observed/expected ratio (o/e) 0.65, 90% interval 0.55 to 0.76. The upper end of that interval is the gene's LOEUF score, 0.76, which puts it in group 3 of 6, group 1 being the genes least tolerant of losing a copy. Missense variants: 1,192 observed, 1,492.8 expected, observed/expected ratio (o/e) 0.8, 90% interval 0.76 to 0.84. Synonymous variants: 477 observed, 555.35 expected, observed/expected ratio (o/e) 0.86, 90% interval 0.8 to 0.93.
Homologues: Orthologues: chimpanzee SPAG5 (98% identical), macaque SPAG5 (94% identical), pig SPAG5 (80% identical), dog SPAG5 (79% identical), rabbit SPAG5 (77% identical), guinea pig SPAG5 (72% identical), mouse Spag5 (66% identical), rat Spag5 (65% identical).
Diseases named in the same sentence as SPAG5 in open-access papers:
SPAG5 is named in the same sentence as 44 diseases in open-access papers, as found by Europe PMC text mining. Sharing a sentence is not in itself a finding about the gene and the disease. The quoted sentences say what the papers report.
breast carcinoma (27 papers, 2013 to 2025). "To assess the activity of SPAG5, we performed loss-of-function assays using siRNA-mediated targeting of SPAG5 in four different breast cancer cell lines: MDA-MB-231, MDA-MB-468, MCF-7, and SUM-159PT." (PMID 33230261, 2021). "The expression of SPAG5 is increased in various tumor tissues, such as breast cancer, prostate cancer, lung cancer, hepatocellular carcinoma, gastric cancer, and cervical cancer, and upregulated SPAG5 is associated with poor prognosis in cancer patients." (PMID 34162370, 2021). "Here, we report that SPAG5 is a direct target of miR-10b-3p, and its aberrantly high expression associates with poor disease-free survival in two large cohorts of breast cancer patients." (PMID 33230261, 2021). "Among them, we focused on sperm-associated antigen 5 (SPAG5), a recently described promoter of breast tumor growth and a poor prognosis marker of breast cancer." (PMID 33230261, 2021). "Because high SPAG5 expression associates with shorter metastasis-free survival in breast cancer patients, we determined the effect of SPAG5 on breast cancer cell migration." (PMID 33230261, 2021). "In conclusion, our observations raised the possibility that miR-10b-3p directly regulates transcripts encoding SPAG5, a gene associated with the aggressive behavior of mammary tumors." (PMID 33230261, 2021). "In this cohort study including 12 720 patients with estrogen receptor–positive breast cancer, SPAG5 transcript and SPAG5 protein overexpressions were associated with worse outcomes in patients who received endocrine therapy alone." (PMID 32633764, 2020). "Our study aimed to investigate the association between SPAG5 and NuMA mRNA levels in breast cancer tumors." (PMID 32838814, 2020). "Are sperm-associated antigen 5 (SPAG5) transcript or protein expressions associated with treatment response in patients with estrogen receptor–positive breast cancer?" (PMID 32633764, 2020). "High SPAG5 expression is a poor prognostic factor for breast cancer and is associated with sensitivity to breast cancer chemotherapy." (PMID 31985007, 2020). "Since SPAG5 gene amplification was also involved in the pathogenesis of the breast cancer, we also intended to identify any association between the amplified genome and SPAG5 / NuMA mRNA levels." (PMID 32838814, 2020). "Among patients with grade 1 breast cancer, high SPAG5 expression was associated with a great increase in risk of recurrence (HR = 2.52, 95% CI 1.4–4.54, p = 0.0014)." (PMID 31690268, 2019). "In some breast cancer subtypes like PR+/ER+ breast cancer, positive SPAG5 expression presented a strong trend toward being associated with lower RFS." (PMID 31690268, 2019). "In breast cancer, we found that high SPAG5 expression was associated with increased local recurrence (p < 0.001)." (PMID 30736840, 2019). "Another module identified among male breast cancers, regulated by SPAG5, was closely associated with proliferation." (PMID 24194916, 2013). "SPAG5 has been implicated in cell proliferation and migration motility in breast cancer." (PMID 38610947, 2024). "Sperm‐associated antigen 5 (SPAG5) is a kind of oncogene in breast cancer." (PMID 37576865, 2023). "Interestingly, high expression of SPAG5 associates with shorter metastasis-free survival in breast cancer patients." (PMID 33230261, 2021). "For breast cancer, the analysis of multiple breast cancer cohorts indicated that high SPAG5 transcript expression was associated with decreased survival in all breast cancer subtypes and estrogen receptor-positive subgroups; although, its prognostic value in TNBC was not clear." (PMID 30736840, 2019). "High SPAG5 expression was associated with more CD8+ T cell infiltration in breast cancer, which suggested SPAG5 could be a potential candidate for future vaccine development." (PMID 30736840, 2019). "One stated the prognostic association of SPAG5 in ER+ breast cancer." (PMID 31690268, 2019).
breast carcinoma (continued). "Validation using UALCAN, GEPIA, and Kaplan-Meier plotters revealed that three key genes-RACGAP1, SPAG5, and KIF20A-were significantly overexpressed and associated with poor prognosis in breast cancer (BC), as well as advanced tumor staging." (PMID 39988630, 2025). "KNSTRN is a SPAG5-binding protein, and SPAG5 has been validated as an independent prognostic biomarker in breast cancer." (PMID 38198023, 2024). "Sperm-associated antigen 5 (SPAG5), also known as Astrin, was previously demonstrated as a biomarker for cellular resistance to major breast cancer therapies, including chemo-, endocrine- and targeted therapy." (PMID 38610947, 2024). "Recent studies have found that SPAG5 is a potential driver oncogene in a wide spectrum of cancers including breast cancer, non-small cell lung cancer, prostate cancer, cervical cancer, and bladder urothelial cancer." (PMID 38610947, 2024). "The transcription of SPAG5 can become unusual and cause this oncogene mutation in the function of YAP/TAZ/TEAD, leading to breast cancer cell proliferation out of control." (PMID 37576865, 2023). "SPAG5 regulates breast cancer progression by regulating cell cycle and correlates with poor prognosis." (PMID 35853859, 2022). "SPAG5 is consistently expressed at higher levels in many types of cancers, such as breast cancer, gastric cancer, cervical cancer, prostate cancer, ovarian cancer, osteosarcoma, hepatocellular carcinoma, bladder cancer and lung cancer." (PMID 35138218, 2022). "Congruently, SPAG5 depletion reduces proliferation and migration of breast cancer cell lines, while its ectopic overexpression confers oncogenic properties to MCF-10A, an untransformed mammary gland cell line." (PMID 33230261, 2021). "In aggregate, our findings uncover a transcriptional and post-transcriptional network that sustains aberrant SPAG5 expression and contributes to breast cancer aggressiveness." (PMID 33230261, 2021). "Taken together, these results validate that SPAG5 serves as a direct target of miR-10b-3p in breast cancer cells." (PMID 33230261, 2021). "To further investigate the oncogenic role of SPAG5 in breast cancer, we set up its stable overexpression in MCF-10A cells." (PMID 33230261, 2021). "In summary, our findings identify a novel transcriptional and post-transcriptional network, which leads to aberrant activation of SPAG5 in breast cancer." (PMID 33230261, 2021). "MDA-MB-468 and MDA-MB-231 breast cancer cells depleted for SPAG5 protein expression accumulated preferentially in the G2 phase of the cell cycle." (PMID 33230261, 2021). "Accordingly, we found that the treatment of breast cancer cell lines with either Dasatinib or Verteporfin and with extracts of Agave reduced SPAG5 expression." (PMID 33230261, 2021). "In order to support the independent role of YAP-TAZ-TEAD axis and SPAG5 in breast cancer development, we conducted an analysis of data from the METABRIC dataset." (PMID 33230261, 2021). "To this end, we used the whole Metabric dataset (N = 1969 patients) and we confirmed YAP signature and SPAG5 as prognostic factors for breast cancer." (PMID 33230261, 2021). "Ectopic expression of miR-10b-3p reduced mRNA and protein levels of SPAG5 in four different breast cancer cell lines: MDA-MB-231, MDA-MB-468, MCF-7, and SUM-159PT, respectively, as well in MCF-10A, an untransformed breast cell line." (PMID 33230261, 2021). "In this section of analyses, we selected from the METABRIC breast cancer dataset, the whole group of cases for which data on SPAG5 expression, YAP signature, and miR- 10b-3p expressions were available at the same time from the same breast cancer cases." (PMID 33230261, 2021). "It was reported that SPAG5 has participated in growth and progression of various tumors, which was overexpressed in breast cancer, osteosarcoma, lung cancer, bladder urothelial carcinoma, prostate cancer, and cervical cancer." (PMID 34796102, 2021).
breast carcinoma (continued). "SPAG5 and NuMA gene expressions were investigated in 40 breast cancer tissues and normal adjacent tissues via real-time PCR." (PMID 32838814, 2020). "This cohort study examines the association of sperm-associated antigen 5 (SPAG5) transcript and protein expression with treatment response in patients with estrogen receptor–positive breast cancer." (PMID 32633764, 2020). "Increased SPAG5 mRNA expression was detected in breast cancer tissues (p = 0.005) and related to tumor size." (PMID 32838814, 2020). "Our results were consistent with the previous publications regarding SPAG5 gene expression and amplification in breast cancer with an emphasis on the prominent role of this protein in tumor pathogenesis." (PMID 32838814, 2020). "The main purpose of this study was to investigate SPAG5 gene expression and amplification related to NuMA mRNA levels in breast cancer tissues." (PMID 32838814, 2020). "Our study highlights the role of increased SPAG5 gene expression and gene amplification in breast cancer." (PMID 32838814, 2020). "SPAG5 has also been linked to the development and metastasis of LUAD, stomach cancer, and breast cancer." (PMID 32528520, 2020). "SPAG5 mRNA expression was upregulated in tumor compared with that in normal tissues in TCGA breast cancer dataset (p < 0.001) and was high in TNBC compared with that in luminal A breast cancer (p < 0.001)." (PMID 30736840, 2019). "SPAG5 protein expression was examined by IHC in 183 breast cancer samples, including 42 TNBC samples." (PMID 30736840, 2019). "In our study, data mining of 5667 publically available gene expression microarrays showed that elevated SPAG5 expression in breast cancer predicted a poor prognosis by the Kaplan-Meier method." (PMID 31690268, 2019). "The potential of SPAG5 as a therapeutic target of breast cancer has been highlighted in some experiments." (PMID 31690268, 2019). "Mean SPAG5 expression value was higher in ER- than ER+ breast cancer patients (mean value 434.48 vs. 602.64, p < 0.001), similar trend was also observed in PR- and HER2+ breast cancer patients." (PMID 31690268, 2019). "c Kaplan–Meier curve of DFS and OS for breast cancer patients with low expression of SPAG5 versus high expression of SPAG5 group." (PMID 30736840, 2019). "Third, the optimal cutoff points of SPAG5 for survival prediction in breast cancer patients still merit further investigation." (PMID 31690268, 2019). "Recently a research team applied an artificial neural network performing data mining functions on SPAG5 and found that SPAG5 expression products were independent predictors for response to chemotherapy in breast cancer." (PMID 31690268, 2019). "Copy number aberration of SPAG5, as well as the high expression of SPAG5 transcript and protein, contributed to the worse overall and cancer-specific survival of patients with breast cancer." (PMID 30089483, 2018). "Amplification or gain of the SPAG5 locus occurring in 10–19% of breast cancers was correlated with poor clinical outcome and adverse clinicopathological features." (PMID 30089483, 2018). "Among those five E2F targets correlated with malignant transition, Cdk1 and Plk1 were well studied in breast cancer, but much less so for Ccnb2, Aurkb, and Spag5 (7, 10, and 3 reports, respectively)." (PMID 28212608, 2017). "The sperm associated antigen 5 (SPAG5) was found to be associated with various types of cancer, such as cervical cancer and breast cancer." (PMID 25945798, 2015). "SPAG5 may have varying degrees of impact on clinical outcomes in different breast cancer cohorts and combination chemotherapy." (PMID 38610947, 2024).
breast carcinoma (continued). "However, previous research into the function of SPAG5 in breast cancer was mainly based on the traditional gene knockdown cell models." (PMID 38610947, 2024). "Moreover, SPAG5 hyperexpression was connected to poor disease-free survival in breast cancer patients, and fueled breast cancer cell proliferation." (PMID 35227274, 2022). "Interestingly, high expression of SPAG5 pairs with a YAP/TAZ-activated signature in breast cancer patients." (PMID 33230261, 2021). "Indeed, we found that Agave markedly reduced SPAG5 mRNA expression and protein expression in both breast cancer cell lines." (PMID 33230261, 2021). "Interestingly, high expressions of SPAG5 associate with lower expression of miR-10b-3p in both METABRIC and TCGA breast cancer datasets and correlate with lower disease-specific survival." (PMID 33230261, 2021). "Previous studies have fully uncovered the clinical impact of SPAG5 in breast cancer." (PMID 34796102, 2021). "Copy number aberration resulting in SPAG5 gain or amplification, as well as the high-level expression of SPAG5 transcript and protein, were accompanied by shorter overall and tumor-specific survival of patients suffering from breast cancer." (PMID 34796102, 2021). "Clinical studies have confirmed the role of SPAG5 in breast cancer prognosis and survival." (PMID 32838814, 2020). "This evidence suggests that SPAG5 may be further studied as a therapeutic target in the treatment of breast cancer." (PMID 32838814, 2020). "This study included 12 720 women aged 24 to 78 years (mean [SD] age, 58.46 [12.45] years) with estrogen receptor–positive breast cancer, including 1073 women with SPAG5 transcript expression and 361 women with SPAG5 protein expression of locally advanced disease stage IIA through IIIC." (PMID 32633764, 2020). "All these were in accordance with our hypothesis described previously that SPAG5 was related to the development of hormone resistance in breast cancer." (PMID 31690268, 2019). "Therefore, we assumed that high SPAG5 expression in breast cancer was potentially more relevant to malignant prognosis in hormonal therapy." (PMID 31690268, 2019). "We found that high SPAG5 expression was associated with lower RFS, OS, and DMFS, and SPAG5 might act as an important marker in systematic therapy, especially in ER+ breast cancer patients who received hormonal therapy." (PMID 31690268, 2019). "Since the oncogenic potential of SPAG5 was also reported in prostate cancer, we hypothesized that SPAG5 could serve as a marker in predicting breast cancer proliferation and progression." (PMID 31690268, 2019). "We observed that high SPAG5 expression was associated with a significant increase in risk of relapse among ER+ (HR = 1.77, 95% CI 1.55–2.03, p < 0.001), but not ER- breast cancer patients (HR = 1.03, 95% CI 0.82–1.28, p = 0.81)." (PMID 31690268, 2019). "Considering the function of SPAG5 in progression of mitosis, these results might imply that early in the etiology of ER+ breast cancer subtypes, SPAG5 contributed to disease progression." (PMID 31690268, 2019). "Thus, in this study, we also investigated the correlation of SPAG5 with CD8 T-cell infiltration in tumor samples of breast cancer patients." (PMID 30736840, 2019). "In conclusion, as a progression-driving oncogene, SPAG5 was closely related to disease progression and malignant prognosis of ER+ breast cancer patients undergoing endocrine therapy, and might act as a therapeutic target for breast cancer." (PMID 31690268, 2019). "SPAG5 could be used as an independent prognostic and predictive biomarker that might have clinical utility, especially in ER+ breast cancer patients who received hormonal therapy." (PMID 31690268, 2019).